STAT3 (signal transducer and activator of transcription 3)
Diseases named in the same sentence as STAT3 in open-access papers (continued):
Sharing a sentence is not in itself a finding about the gene and the disease.
tumor (continued). "On the other hand, the activation of NF-κB/STAT3 pathway stimulates the expression of immune/inflammatory cells attracting mediators, which sustain tumor-associated inflammation." (PMID 32731512, 2020). "IL-6 promotes tumor cell proliferation by acting through the STAT3 pathway to upregulate Myc expression and induces the expression of anti-apoptotic genes encoding bcl2, bcl-XL and survivin to promote tumor survival." (PMID 33076397, 2020). "CTLA4apt-STAT3 siRNA can lead to internalization into tumor-associated CD8+ T cells and inhibit the expression of STAT3, which can activate the tumor antigen-specific T cells." (PMID 33123281, 2020). "The migration and invasion of cancer cells into the bloodstream and surrounding tissues are critical steps in cancer metastasis, and the transcription of target genes associated with these processes is regulated by STAT3 in the tumor microenvironment." (PMID 32183406, 2020). "The FGFR4 Arg388-variant enhances STAT3 signaling, promotes tumor progression, and is associated with poor prognosis of multiple cancers." (PMID 32154250, 2020). "IL-6 produced by tumor-associated macrophages (TAMs) can activate the STAT3 signaling pathway to promote CD44+ LCSCs." (PMID 33117795, 2020). "Persistent activation of STAT3 is linked to tumor-associated angiogenesis, where STAT3 is capable of modulating the stability and activity of HIF-1α, resulting in enhanced VEGF expression." (PMID 33003453, 2020). "Abnormal activation of JAK/STAT3 signaling is associated with tumor progression, tumor microenvironment, and immune evasion." (PMID 32265690, 2020). "We and others, have previously shown a correlation between activated STAT3 pathway and the existence of chemoresistance-associated CSCs in residual tumours." (PMID 33023532, 2020). "It has been reported that HER2-induced secretion of IL-6 can act in an autocrine fashion in human tumor cells causes STAT3-mediated gene expression and signaling activation and facilitates oncogenic growth." (PMID 32683421, 2020). "STAT-3 activation can also be linked with proliferation of tumor cells, becauseit induces the expression of cyclin D1 (Masudaet al., 2002)." (PMID 32167126, 2020). "In tumor-associated myeloid-derived suppressor cells (MDSCs), STAT3 was required for the induction of angiogenic factors, including VEGF and bFGF, and increased angiogenesis in vitro." (PMID 32486098, 2020). "It showed that the STAT3 score, nuclear STAT3 score, pathological stage lymph node involvement, lymphovascular invasion, and tumor grade were associated with both progression-free survival and cancer-specific survival." (PMID 32102537, 2020). "FGFs and FGFRs are involved in different physiological processes and tumor development associated with proliferation, survival, differentiation, migration, and apoptosis by activating the STAT3, MAPK, and other pathways." (PMID 32432040, 2020). "It has been reported that in the tumor microenvironment, the IL-6/STAT3 signaling pathway plays an important role in the macrophage M2 polarization, and activation of the IL-6/STAT3 signaling pathway causes macrophages to polarize towards the M2 phenotype." (PMID 32904108, 2020). "In our analysis, the high correlation between the immune-related gene signature-based risk score and the IL-6/JAK/Stat3 pathway highlighted the tumour-promoting effect of the IL-6/JAK/Stat3 pathway in early-stage LUAD." (PMID 32333046, 2020). "AMPK has been implicated in the inhibition of tumor proliferation via suppression of STAT3 activation." (PMID 31952344, 2020).
tumor (continued). "p-STAT3 acts in turn induces M2 polarization of tumor-associated macrophages, which ultimately contribute to the development of the metastatic phenotype of EOC cells." (PMID 33228245, 2020). "A regulatory complex was also identified between STAT3 and those chromatin-associated enzymes in epigenetic silencing or activation of vital tumor-promoting genes." (PMID 32041943, 2020). "The association between Hsp90 and STAT3 was identified in tumor cells, and is necessary for STAT3 phosphorylation, dimerization, and nuclear translocation, all of which contribute to cancer cell survival." (PMID 33390934, 2020). "Cells carrying a mutation in the mitochondrial localization sequence of STAT3 displayed a slower tumor growth rate." (PMID 33266219, 2020). "They found that stabilization of HIF-1α and increased phosphorylation of the signal transducer and activator of transcription 3 (pSTAT3), in tumor cells, were associated with evasion of immune surveillance." (PMID 33117715, 2020). "Despite the multifaceted function of STAT3 in cancer, growing evidence has revealed that constitutive activation of STAT3 contributes to cancer cell proliferation and that aberrant STAT3 activation is associated with tumor malignancy." (PMID 33371351, 2020). "Intriguingly, a decrease in MDSC STAT3 activity in the tumor environment is associated with differentiation into TAMs." (PMID 33519825, 2020). "This resulted in increased production of IL-6 by IL-17 receptor-expressing tumor and tumor-associated stromal cells and concomitantly increased STAT3 signaling and production of pro-survival Bcl-2 and Bcl-xL in melanoma cells." (PMID 32517051, 2020). "These investigations present credible clues for NAT regulation of NF-κB/STAT3, and shed light on tumor-associated inflammation." (PMID 32928281, 2020). "In contrast, M2 polarization, associated with immune suppression and tumor progression, is induced by STAT3 and STAT6 activation." (PMID 32133045, 2020). "A recent study showed KLF5 disruption can reduce STAT3 activation, and cause tumor regression in vivo." (PMID 33424607, 2020). "Aberrant STAT3 activity, as seen in several cancer types, is associated with tumour progression and malignancy, in addition to propagating crosstalk between tumour cells and the microenvironment." (PMID 32731620, 2020). "A particular subset of macrophages, named tumor-associated macrophages (TAMs), are activated by cancer cells and promote the production of inflammatory cytokines through a STAT3 pathway." (PMID 32331450, 2020). "Based on these studies, CD44 and STAT3 have overlapping functions within tumor-associated regulatory T cells." (PMID 33335857, 2020). "Our data support the idea that JAK/STAT3 signaling plays a pivotal role in transcriptional reprogramming associated with pericyte recruitment and activation after tumor interaction." (PMID 32756477, 2020). "Our results show that Imaging-AMARETTO recapitulates known key drivers of tumor-associated microglia and macrophage mechanisms (STAT3, AHR, and CCR2) and neurodevelopmental and stemness mechanisms (OLIG2)." (PMID 32383980, 2020). "The presence of REG3β triggers M2 polarization through the activation of the STAT3 signaling pathway, while its deficiency led to a decrease in the M2/M1 ratio in the tumor area." (PMID 33505964, 2020). "Hyperactivation of STAT3 in tumor-infiltrating immune cells causes immunosuppression by inhibiting both innate and adaptive immune responses." (PMID 32972405, 2020). "A TLR9/IL-6/JAK/STAT3 pathway in tumor-associated myeloid cells plays an essential role in initiating the cancer recurrence after radiotherapy." (PMID 32788720, 2020). "CSC properties and metastatic capabilities are implicated with tumor malignancy, recurrence and drug resistance in various types of cancer, which are closely associated with STAT3 signaling in the inflammatory tumor microenvironment." (PMID 32183406, 2020).
tumor (continued). "Lung epithelial-specific deletion of STAT3 before urethane-induced cancer formation increased K-RAS mutation rates and tumor numbers, while STAT3 deletion after urethane-treatment reduced tumor cell proliferation and tumor growth." (PMID 32365499, 2020). "Most astrocytes found in brain metastases were recently shown to express the phosphorylated (activated) form of STAT3 (pSTAT3), suggesting that STAT3 signaling also plays a key role in the tumor-associated cells." (PMID 32399646, 2020). "It is well established that nuclear factor-κB/signal transducer and activator of transcription 3 (NF-κB/STAT3), the well-defined regulatory hubs of tumor-associated inflammation, play pivotal roles in maintaining the delicate crosstalk." (PMID 32928281, 2020). "The most significant biological processes that appear to negatively correlate with the immune risk are IFN-α responses, IFN-γ responses, IL-2/STAT5 signaling and IL-6/JAK/STAT3 signaling, all of which were associated with tumor immunity." (PMID 31988638, 2020). "The activation of STAT3 was markedly increased by a W775 stop germline mutation of protein tyrosine phosphatase delta, a tumor suppressor, identified in 37.5% of metastatic ES patients." (PMID 32754598, 2020). "For example, STAT3 increased CTLA-4 expression in tumor-associated B cells in a JAK-dependent manner and enhanced CTLA-4 expression in Treg cells through IL-10." (PMID 32972405, 2020). "Dysregulation of NF-κB/STAT3 will upset the delicate balance, leading to a predisposition to the pro-tumorigenic direction and ultimately driving tumor initiation and progression." (PMID 32928281, 2020). "B7-H3 has recently been associated with increased STAT3 activity, leading to further angiogenesis in tumor cells." (PMID 32992699, 2020). "STAT3 is an important mechanism for inducing the activation of tumor-associated macrophages M2 type." (PMID 32904108, 2020). "For example, preclinical findings have identified that inhibition of the interleukin-6 (IL-6)/STAT3 pathway can also inhibit tumor growth with EGFR mutation in NSCLC and suppress KRAS-driven lung adenocarcinoma." (PMID 33537237, 2020). "Consistently, CADPE suppressed CRC tumor growth associated with robust apoptosis and depleted levels of c-Myc, STAT3, NF-κB, eIF4F, anti-apoptotic proteins, and pro-stemness proteins." (PMID 33191401, 2020). "This profile revealed that the lower expression of STAT3 caused by astaxanthin effectuated anti-tumor functions." (PMID 32784629, 2020). "The deletion of Stat3 in prostate epithelial cells in a loss of Pten PCa mouse model leads to increased tumor growth and early death." (PMID 32323921, 2020). "As a well-known transcription factor, STAT3 is implicated in the proliferation, migration, and invasion of various tumor cells depending on its active form, pSTAT327." (PMID 33082325, 2020). "For a long time, STAT3 has been regarded as a driver of tumor malignancy and its activation is associated with worse clinical outcome." (PMID 30718461, 2019). "STAT3 and NFκB activities have been associated with different leukocyte phenotypes and anti-tumor responses." (PMID 30840689, 2019). "Particularly, G9a was reported to reduce the expression levels of microRNAs, such as miR-200c, under the mediation of STAT3-G9a, which causes the astrocyte leptin receptor to exacerbate tumor progression in breast cancer." (PMID 31619200, 2019). "Aberrant activation of AKT, ERK, STAT3, and Smad2/3 was reported to be closely associated with hepatocarcinogenesis and tumor progression 13-16." (PMID 31754332, 2019). "MiR155 contributes to impaired T cell-dependent antibody response, promotes production of both monocytic and granulocytic MDSCs and induces chemoresistance through C/EBPβ/IL6/IL6R/STAT3 signaling axis in tumor-associated macrophages." (PMID 30925928, 2019). "Some authors believe that Stat3 activation is the key factor responsible for the tolerance associated with tumor escape from the immune surveillance." (PMID 31709183, 2019).
tumor (continued). "Accumulating pre-clinical and clinical studies indicate that the tolerogenic properties of GB and tumor-associated myeloid cells are highly controlled by the signal transducer and activator of transcription 3 (STAT3), an oncogenic transcription factor." (PMID 31698775, 2019). "STAT3-induced cytokines are important mediators of the crosstalk between tumor cells, tumor-associated macrophages (TAMs), and tumor-associated neutrophils (TANs), which are responsible for generating a pro-metastatic and pro-angiogenic TME." (PMID 31684144, 2019). "Activated STAT3 can be either pro-oncogenic or tumor-suppressive according to the tumor etiology and mutational landscape, and it considers as a critical transcription factor for Th17 differentiation, while represses the development of Tregs." (PMID 31024835, 2019). "Tumor development in the liver has been widely linked to macrophage-mediated chronic inflammation in which epidermal growth factors, STAT3 and NF-kβ are some of the most relevant signaling molecules involved." (PMID 31921146, 2019). "The constitutive activation of STAT3 in cancer is caused mostly by the higher secretion of cytokines and growth factors in tumor microenvironment." (PMID 31781335, 2019). "The anti-tumor effects of STAT3 decoy are associated with reduced tumor cell proliferation, induction of apoptosis, and reduced expression of STAT3 target genes, including the genes encoding Bcl-XL and cyclin D1." (PMID 31671769, 2019). "While STAT3 is known to be overexpressed in tumor cells, it is also dysregulated in tumor-associated myeloid cells, such as dendritic cells and macrophages." (PMID 31671769, 2019). "Where increased STAT3 activation is associated with tumor progression, it is often the loss of STAT1 and the associated pathway components that have been most widely explored in the context of cancer and immunity." (PMID 31842362, 2019). "Our results suggest that STAT3 expression is significantly associated with poor tumor histological differentiation and the presence of distant metastases, the two features of GC previously shown to be tightly related to pronounced EMT." (PMID 31234597, 2019). "Selective targeting of STAT3 in tumor-associated myeloid-derived cells is possible with siRNA conjugation to a CpG TLR-9 ligand." (PMID 31671769, 2019). "Interesting, the tumor-promoting effects of Smad7 are linked to activation of NFκB and Stat3 signaling in these mouse models." (PMID 31614569, 2019). "Proteomic and DNA methylation analyses revealed tumor-specific signatures linked to the evolutionary conserved oncogenic STAT3." (PMID 30645971, 2019). "Of importance, persistent STAT3 activation was particularly observed in the most invasive mesenchymal GB subtypes, regulating epithelial mesenchymal transition and tumor progression, associated with a worse prognosis." (PMID 31698775, 2019). "We showed that pacritinib treatment significantly reduced cell viability and colony/tumor sphere formation in association with reduced levels of STAT3, Sox2, PDCD4, and miR-21; it also reduced the ability to generate M2 GAMs." (PMID 31269723, 2019). "Among these transcription factors was STAT3, which can have an oncogenic or tumor suppressor role depending on the mutational status of the tumor or the methylation status of the HoxA5 promoter, resulting in a loss of expression." (PMID 31040909, 2019). "In the treatment of metastatic liver cancer with the EGFR inhibitor cetuximab, the tumor drug resistance is also associated with activation of STAT3." (PMID 30674340, 2019). "As a signal transducer and transcription factor, STAT3 is frequently activated in cancer cells and associated with cell proliferation, inhibition of apoptosis, and tumor progression." (PMID 31092229, 2019). "Tumor-initiating stem cells have been reported to potently express ObR, resulting in tumor progression mediated by the activation of STAT3 and induction of pluripotency-associated transcription factors, such as Oct4 and Sox2." (PMID 31141984, 2019).
tumor (continued). "The IL-6/STAT3 signaling pathway has also been implicated as a link between inflammation and tumor development." (PMID 30832202, 2019). "PVT1, which is associated with tumor progression and predicts recurrence, directly interacted with STAT3, increased its protein stability, and inhibited poly-ubiquitination and proteasome-dependent degradation." (PMID 31028131, 2019). "A combination of RNA sequencing, whole exome sequencing, and Sanger sequencing on tumor samples from patients with NKTCL revealed that 5.9% had activating STAT3 mutations, while 8.3% of tumors from γδ PTCL patients harbored these mutations." (PMID 31684088, 2019). "miR-369-5p is associated with tumor migration, whereas miR-151-3p inhibits lipopolysaccharide (LPS)-induced IL-6 production by targeting STAT3." (PMID 31694199, 2019). "For example, inflammatory monocytes and mo-MDSCs migrate and rapidly differentiate toward tumor associated macrophages (TAM) in tumor tissues, reducing the activity of the transcription factor STAT3." (PMID 31683978, 2019). "The in vivo anti-tumor effect was associated with increased apoptosis and combined inhibition of the STAT3 and EGFR pathways in tumor remnants." (PMID 30674340, 2019). "NF-κB and STAT3 can enhance the expression of IL-6, creating a feed-forward loop implicated in tumor development, progression, and metastasis." (PMID 31557902, 2019). "Our mouse xenograft model also confirmed that decreased SIX1 abundance was associated with significantly reduced tumor volume and suppression of STAT3 signaling." (PMID 31921695, 2019). "Significantly, the GBM cohorts harboring a high-level H2AFJ transcript combined with high-level expression of TNF-α/NF-κB geneset, IL-6/STAT3 geneset or HADC3 were associated with a shorter time to tumor repopulation after initial treatment with TMZ." (PMID 31906036, 2019). "Persistent activation of STAT3 was detected in many human malignancies and linked to mechanisms of proliferation, invasion of malignant cells, angiogenesis and inhibition of anti-tumor immunity." (PMID 31342143, 2019). "At these pre-metastatic sites, persistent STAT3 phosphorylation was associated with myeloid cell migration from the primary tumor to the secondary site." (PMID 31684144, 2019). "Conversely, STAT3 has been widely linked to cancer cell survival, immunosuppression, and sustained inflammation in the tumor microenvironment." (PMID 31842362, 2019). "Given the spectrum of STAT3-regulated genes in TAM encoding pro-tumor and immune suppressive mediators, STAT3-modulators are currently being developed to dampen the cancer supportive functions of TAM, as reported in this issue by Rébé and Ghiringhelli." (PMID 31766350, 2019). "Stat3-enhanced chemoresistance in lung malignant cells were suppressed by introduction of Stat3 siRNA thus causing the tumor cells more responsive to paclitaxel." (PMID 30847297, 2019). "Despite the connection between increased STAT3 activity and neoplastic disease, as well as the observation that somatic GOF mutations in STAT3 lead to malignancies, neoplastic disease was quite rare in previously reported cohorts." (PMID 31799221, 2019). "For instance, U87MG and LN18 GBM cells cocultured with clinical M2 GAMs showed increased colony-forming and tumor-sphere-generating abilities in association with increased stemness markers Sox2, STAT3, Wnt, and Nestin in the GBM cells." (PMID 31269723, 2019). "Constitutive STAT3 activation promotes accumulation of microglia and M2 tumor-associated macrophages (TAMs) that suppress anti-tumor mechanisms and induce tolerance to tumor antigens along with a proangiogenic potential." (PMID 31698775, 2019). "In the present study, we showed how NLGP modulates tumor-associated MSCs by reducing their IL-10 secretion that ultimately results in reduced phosphorylation of STAT3 leading to enhanced transcription of cystathionase in DCs." (PMID 31547863, 2019).